EP400P1 (EP400 pseudogene 1)
Description:
May be a component of a SWR1-like complex that displays H2A.Z deposition activity and is involved in transcription initiation-coupled chromatin remodeling. The SWR1-like complex lacks histone acetyltransferase activity.
Synonyms: FLJ33915; formerly EP400NL
Gene: Transcribed unprocessed pseudogene on chromosome 12 (132,104,021 to 132,127,177, forward strand). Ensembl gene ENSG00000185684.
Subcellular location: Nucleus